Y_RNA (Y RNA )
Gene: Miscellaneous RNA gene on chromosome 12 (7,976,259 to 7,976,360, forward strand). Ensembl gene ENSG00000206636.
Homologues: Orthologues: chimpanzee Y_RNA (98% identical). Paralogues in human: Y_RNA (85% identical), Y_RNA (84% identical), RNY3 (83% identical), Y_RNA (83% identical), RNY3P1 (82% identical), RNY3P11 (82% identical), RNY3P14 (82% identical), Y_RNA (82% identical), RNY3P7 (81% identical), Y_RNA (81% identical), RNY3P2 (80% identical), Y_RNA (80% identical), and 93 more.